EMD (emerin)
Diseases named in the same sentence as EMD in open-access papers (continued):
Sharing a sentence is not in itself a finding about the gene and the disease.
muscular dystrophy (continued). "In this study, we applied segregation analysis and emerin immunostaining on myocardial tissue to verify the causality of a missense variant in the EMD gene to X-linked DCM without muscular dystrophy in a large family, thereby providing new evidence linking the EMD gene to isolated DCM." (PMID 40065010, 2025). "Further, there are muscular dystrophies with similar symptoms to FSHD, that are linked with genes of the nuclear envelope: striated muscle laminopathies (e.g. Emery–Dreifuss-muscular-dystrophy and limb-girdle-muscular-dystrophy 1B) are caused by mutations in EMD, LMNA or SYNE1, among others." (PMID 38796645, 2024). "In addition, mutations in both EMD and LMNA are involved in the Emery–Dreifuss muscular dystrophy." (PMID 33722199, 2021). "However, intermittent STAT3 inhibition may have promising implications for increasing muscle regeneration in emerin-related muscular dystrophy." (PMID 34206382, 2021). "Conversely, activated STATs that are not under the control of the emerin network lead to increased expression of genes associated with muscle cell proliferation, and this imbalance may lead to myofiber regeneration problems such as muscular dystrophy." (PMID 34206382, 2021). "The dataset includes 13 muscular dystrophy related phenotypes, i.e. ALS, AQM, BMD, Calpain3, DMD, Dysferlin, Lamin A/C, Emerin, FKRP, FSHD, HSP, JDM, and NHM." (PMID 18801195, 2008). "This study provides new support for an association between the EMD gene and DCM without muscular dystrophy, by presenting evidence of co-segregation in a large family, emerin deficiency in the myocardium and skeletal muscle, and normal neuromuscular examinations." (PMID 40065010, 2025). "Thus, representative muscular dystrophy, X-EMDM, is presumed to cause problems in several biological processes due to the lack of emerin." (PMID 34206382, 2021).
cardiomyopathy (19 papers, 2014 to 2026). A disease of the heart muscle or myocardium proper. "Loss-of-function mutations in EMD, the gene that encodes emerin, cause X-linked Emery–Dreifuss muscular dystrophy and cardiomyopathy in humans." (PMID 37108075, 2023). "This study has the inherent limitations associated with the use of LmnaH222P/H222P mice to observe emerin deficiency in cardiac muscle; however, EH mice demonstrate a relatively similar progression of cardiomyopathy to H222P mice." (PMID 37940872, 2023). "Most reported mutations in the EMD gene caused apparent skeletal muscle disorders with cardiomyopathy in the form of EDMD." (PMID 24997722, 2014). "Emery–Dreifuss muscular dystrophy (EDMD) is a rare inherited myopathy characterized by early-onset contractures of major tendons, progressive skeletal muscle wasting, and cardiomyopathy, most often caused by mutations in the nuclear envelope proteins emerin (EMD) or lamin A/C (LMNA)." (PMID 40558510, 2025). "Likewise, emerin-linked diseases frequently display prominent cardiac involvement, and cardiomyopathy may precede skeletal muscle symptoms in EDMD patients." (PMID 41596589, 2026). "Among the detectable markers of cardiomyopathy, we evaluated the activation of mTOR, AKT, Smad3, and ERK1/2 to investigate the association of emerin and lamin A/C in the regulation of signaling pathways associated with cardiomyopathy." (PMID 37940872, 2023). "A branch of the MAPK signaling cascade, the extracellular signal-regulated kinase (ERK), has been shown to be abnormally activated in cardiomyopathy associated with EDMD caused by mutations in the LMNA and EMD genes." (PMID 29192166, 2017). "Similarly, the inner nuclear envelope protein emerin, encoded by the EMD gene, is the cause of EDMD type 1, which is associated with cardiomyopathy in a majority of cases." (PMID 39519012, 2024). "Taken together, several cardiomyopathy-associated genes were altered in both H222P and EH mice, compared with WT and Emd mice: however, were not notably changed by emerin deficiency in mice with the Lmna mutation." (PMID 37940872, 2023). "Thus, recessive loss of emerin leads to X-linked EDMD, a severe envelopathy characterized by progressive muscle wasting and cardiomyopathy with conduction defects." (PMID 36377660, 2022). "Furthermore, we showed that different genes involved in cardiomyopathies like emerin (EMD), nuclear factor of kappa light polypeptide gene enhancer in B-cells 1 (NFKB1) are under the control of specific miRNAs." (PMID 24699212, 2014). "Consistent with the functional importance of emerin–lamin interactions, clinical studies have demonstrated that cardiomyopathy can precede skeletal muscle symptoms in EDMD patients, indicating that cardiac involvement may represent an early manifestation of disease." (PMID 41596589, 2026). "Several murine models for EDMD have been generated; however, emerin-null (Emd) mice do not show obvious skeletal and cardiac muscle phenotypes, and LmnaH222P/H222P mutant (H222P) mice show only a mild phenotype in skeletal muscle when they already have severe cardiomyopathy." (PMID 31430335, 2019).
laminopathies (19 papers, 2007 to 2025). "These functions are critical for proper myogenic differentiation and are closely linked to the pathology of Emery‐Dreifuss muscular dystrophy 1 (EDMD1), a laminopathy caused by mutations in the EMD gene." (PMID 40178931, 2025). "For example, laminopathies are rare genetic diseases caused by mutations of genes encoding the NE proteins such as Lamin A/C (Lamin), Emerin (EMD), and Nesprins (SYNE1/2)." (PMID 33490050, 2020). "Indeed, only three emerin ExAC variants were previously reported in the laminopathy database: p.K37del, p.R203H and p.D149H." (PMID 31024910, 2019). "Recently, Shin and Worman summarized the molecular pathology of laminopathies, unveiling mechanisms of cardiomyopathic disease that are tightly related to emerin and lamin, which are critical for the nuclear envelope." (PMID 40099194, 2025). "Laminopathies and emerinopathies are genetic disorders caused by mutations in LMNA and EMD genes, respectively, encoding lamin A/C and emerin—ubiquitous proteins of the nuclear envelope." (PMID 33673224, 2021). "Secondary laminopathies, which are caused by mutations in the LMNB1 or LMNB2 genes, ZMPSTE24 or in genes encoding for lamin-binding proteins (e.g., EMD/emerin) were also described." (PMID 32471220, 2020). "The best-known laminopathy phenotypes are based on mutations in the LMNA gene (autosomal), which encodes for lamins A and C, and the EMD gene (X-linked), which encodes for emerin." (PMID 27534416, 2017). "Mutations in genes encoding for lamins and lamina-associated proteins, such as LEM domain proteins (LAP2, emerin, and MAN1), cause human genetic disorders that are collectively referred to as laminopathies or envelopathies." (PMID 27534416, 2017). "Dysregulation of genes involved in organizing and maintaining nuclear structures, such as SYNE1, SYNE2, TREM43, EMD and LMNA is frequently associated with diverse diseases termed laminopathies, which often affect the muscle tissue." (PMID 25906157, 2015). "In addition to lamin, nesprin 2 and other LINC proteins, Sun1 and emerin, have been implicated to involve in the pathogenesis of progeria or EDMD of the laminopathies." (PMID 32815283, 2020). "Moreover, given that mutations in emerin and BAF result in progeria and laminopathies, defects in the regulation of their interaction could potentially contribute to human disease." (PMID 37463656, 2023). "A recent report showed that in laminopathies, especially in EDMD1, we might face some discrepancy in misidentification of so-called emerin-null patients, and some emerin-null phenotype mutations (e.g., c.450 − 2A > G) are misdiagnosed because of improper selection of emerin antibodies." (PMID 30871242, 2019). "Interestingly, different sets of mutations in the LMNA gene and genes coding for interacting proteins, such as emerin (EMD/STA gene) and BAF (barrier-to-autointegration, BANF1 gene), give rise to a variety of genetic disorders collectively called laminopathies." (PMID 30691039, 2019).
X-linked Emery-Dreifuss muscular dystrophy (14 papers, 2004 to 2025). X-linked form of Emery-Dreifuss muscular dystrophy. "Cardiac involvement has become a major threat to patients with EDMD1; however, the cardiovascular phenotype spectrums of emerinopathy and the mechanisms by which emerin regulates cardiac pathophysiology remain unclear." (PMID 36106556, 2022). "As such, discovering the potential mechanism linking emerin and PGC1α might facilitate reliable therapeutic targets for cardiac emerinopathy." (PMID 36106556, 2022). "Thus, a comprehensive understanding of the upstream mechanisms by which emerin regulate mitochondrial function would be a future direction of research favourable for investigating therapeutic strategies and genetic manipulations aimed to treat cardiac emerinopathy." (PMID 36106556, 2022).
prostate carcinoma (6 papers, 2020 to 2025). A carcinoma that arises from epithelial cells of the prostate gland. "Emerin is also found in micronuclei present in prostate cancer cells, with its subsequent loss at the NE." (PMID 39866838, 2025). "Taken together, our data suggest that the formation of Emerin-rich MN, which results in functional pauperization of Emerin at the nuclear envelope, causes a specific phenotypic switch in prostate cancer cells, ultimately resulting in more invasive behavior strongly linked to a worse prognosis." (PMID 39218980, 2024). "LNCaP, an early model of prostate cancer, shows maintenance of lamin B1 and emerin similar to the most aggressive model DU145 while intermediate model PC3 shows loss of lamin B1 and emerin enrichment." (PMID 40060436, 2025). "With respect to emerin, knockdown of emerin in the prostate cancer cell lines DU145, PC3 and LNCaP resulted in altered nuclear morphology and increased migration and invasiveness." (PMID 39115711, 2024). "Deformed nuclei and the mislocalization and low expression of lamin A/C, lamin B1, and emerin became more prominent as the invasiveness of the prostate cancer lines increased." (PMID 39115711, 2024). "The study involved analyzing cells for Emerin distribution, observing the effects of Emerin misplacement on cell movement and invasiveness, and examining prostate cancer tissue to see how these findings relate to the disease in patients." (PMID 39218980, 2024). "Circulating tumor cells from prostate cancer patients were shown to have Emerin mislocalization, and the DU145 prostate cancer cells with EMD silencing formed widespread metastases more efficiently in a mouse model." (PMID 39218980, 2024). "Emerin, which interacts with lamin A/C can also affect metastatic potential and nuclear shape in prostate cancer cell lines with emerin knockdown in DU145 cells resulting in greater metastatic potential." (PMID 33316938, 2020). "Targeting the pathways leading to Emerin misplacement could offer novel strategies for treating aggressive prostate cancer." (PMID 39218980, 2024). "This research investigates how micronuclei may contribute to cancer progression, in the context of prostate cancer, by focusing on the nuclear envelope protein, Emerin." (PMID 39218980, 2024). "Immunofluorescence data reveal that human HT1080 fibrosarcoma and PC3 prostate cancer cell lines showed a MEF-like heterogenous decrease of lamin B1 in the nuclear bleb relative to the nuclear body while emerin levels could be enriched, similar, or depleted in the bleb." (PMID 40060436, 2025). "Additionally, CTCs from prostate cancer patients were shown to have reduced emerin expression." (PMID 33316938, 2020). "Our studies of LNCaP cells, an early-stage prostate cancer model, reveal nuclear blebs that maintain lamin B1 and emerin levels without rupture." (PMID 40060436, 2025). "Immunofluorescence data revealed that human HT1080 fibrosarcoma and PC3 prostate cancer cell lines show a MEF-like heterogenous decrease of lamin B1 in the nuclear bleb relative to the nuclear body, with emerin levels that could be relatively enriched, maintained or depleted." (PMID 41047936, 2025).
breast carcinoma (3 papers, 2021 to 2025). "Given the Lem-D transcripts, Ankle2, TMPO, Emerin, and Lemd2, were overexpressed in breast cancer patient samples and overexpression largely associated with poorer patient outcomes, we next investigated whether the Lem-D proteins were similarly overexpressed in TNBC cell lines." (PMID 38720803, 2024). "Specifically, a reduction of emerin by 40–50% in invasive breast cancer cells compared with control cells led to structural abnormalities in the nucleus previously associated with increased cell migration, intravasation, and extravasation." (PMID 39866838, 2025). "GENT2, TCGA, and KM plotter were utilized to investigate the expression and prognostic implications of several Lem-D proteins: Ankle2, TMPO, Emerin, and Lemd2 in publicly available breast cancer patient data." (PMID 38720803, 2024). "There is evidence to suggest that Ankle2, TMPO, Emerin, and Lemd2 expressions are correlated with breast cancer patient outcomes, but larger patient sample numbers are required to confirm this." (PMID 38720803, 2024). "Our findings also demonstrated that EMD expression was shown to negatively correlate with patient outcomes suggesting a possible role for Emerin in breast cancer cell growth and proliferation." (PMID 38720803, 2024). "Lastly, emerin has emerged as a likely mediator of nuclear shape stability in prostate, lung, and breast cancer." (PMID 34681951, 2021). "We demonstrate EMD transcript overexpression in breast cancer patient samples." (PMID 38720803, 2024). "Furthermore, the interaction of emerin with HDAC3 is important for invasive breast cancer cell invasion and metastasis." (PMID 34681951, 2021).
heart failure (3 papers, 2019 to 2024). Inability of the heart to pump blood at an adequate rate to meet tissue metabolic requirements. "EDMD2 caused by mutations in LMNA leads to more severe ventricular dysfunction and heart failure compared with emerin-deficient EDMD1." (PMID 37940872, 2023). "Nonsense mutations in the EMD gene and lack of emerin expression lead to Emery–Dreifuss muscular dystrophy (EDMD), an X-linked recessive disease that causes degenerative skeletal muscle wasting, heart failure, and early death." (PMID 31771260, 2019).
lipodystrophy (3 papers, 2017 to 2019). A congenital or acquired disorder characterized by abnormal loss or redistribution of the adipose tissue in the body. "The common duplication of PMP22 was ruled out by clinical-grade testing, and genes known to cause lipodystrophy (LMNA, PPARG, EMD, AGPAT2, BSCL2) were also sequenced." (PMID 28050599, 2017). "The emerin p.D149H phenotype is opposite to that seen in LMNA-associated metabolic disease, especially for triglycerides and waist circumference, both of which are elevated in LMNA-associated lipodystrophy, insulin resistance and metabolic syndrome." (PMID 31024910, 2019).
Skeletal myopathy (3 papers, 2014 to 2025). "In addition to DCM in the first decades of life, Emery–Dreifuss muscle dystrophy (EDMD) generates skeletal myopathy secondary to mutation in the lamin A/C (LMNA) gene with autosomal dominant inheritance or mutation in the EMD gene with X-linked recessive inheritance." (PMID 38337354, 2024). "Different from the typical clinical features caused by the majority of reported EMD mutations, the patients in our study present severe DCM but very mild skeletal muscle disorder." (PMID 24997722, 2014).
cardiac conduction disease (2 papers, 2021 to 2022). "This study also found that mutations in emerin have been linked to the development of DCM, cardiac conduction disease (CCD), atrial fibrillation (AF), LGMD and rigid spine syndrome (RSS)." (PMID 36552829, 2022). "The results identified a novel duplication mutation (c.405dup/p.Asp136X) in emerin gene in this family, suggesting the necessity of testing for emerin gene mutations in patients with cardiac conduction disease and SCD of X-linked inheritance with and without neuromuscular phenotypic features." (PMID 33567613, 2021).
HIV-1 infection (2 papers, 2010 to 2014). The type species of lentivirus and the etiologic agent of acquired immunodeficiency syndrome (AIDS). "A third experimental approach based on the use of dominant negative emerin molecules presenting mutations in the LEM domain confirmed that HIV-1 infections occur even in the presence of high levels of mutant proteins." (PMID 20374633, 2010). "The group of Stevenson proposed that emerin, as well as LAP2α, was required for HIV-1 infection in Mφ to assist the targeting of HIV DNA to the chromatin." (PMID 20374633, 2010). "In addition, binding partners of emerin, the LEM (LAP2 (lamina-associated polypeptide 2)/emerin/MAN1) is necessary for the interaction of viral cDNA with emerin and capability of emerin to support HIV-1 infection in macrophages." (PMID 26056579, 2014). "The same results were found in Mφ from wild-type and knockout mice transduced with HIV-1, indicating that emerin and LAP2α are dispensable for HIV-1 infection in mouse/human dividing/non-dividing cells." (PMID 20374633, 2010). "However, Shun and colleagues demonstrated that HIV-1 can efficiently infect dividing cells despite of the absence of emerin, suggesting the role of emerin in HIV-1 infection restricted to only macrophages." (PMID 26056579, 2014).
melanoma (2 papers, 2017 to 2025). A malignant, usually aggressive tumor composed of atypical, neoplastic melanocytes. "Consistently, a different study found that enhanced emerin expression increased nuclear stiffness in melanoma cells." (PMID 39866838, 2025). "Alterations in nuclear stiffness, leader bleb area, and subsequent melanoma migration were contingent on emerin being correctly localized at the INM." (PMID 39866838, 2025). "Analyses in primary melanoma and melanoma cell lines indicated that MAPRE3 and EMD mRNA levels were not substantially changed compared to primary normal human epidermal melanocytes (NHEM)." (PMID 28423600, 2017).